MPO (myeloperoxidase)
Diseases named in the same sentence as MPO in open-access papers (continued):
Sharing a sentence is not in itself a finding about the gene and the disease.
liver disease (15 papers, 2018 to 2025). "In HBV-associated liver disease, combining MPO-DNA with routine liver function tests improves the accuracy of predicting 90-day mortality in ACLF patients, providing a basis for liver support therapy or transplantation evaluation." (PMID 41156629, 2025). "We whether elevation of MPO associated with kidney and liver disease risk in subgroups stratified by ASCVD risk and intensity of therapy." (PMID 40210927, 2025). "Hepatic deposition of fibronectin and types I and III collagen also decreased, alongside with reductions in reactive oxygen species and myeloperoxidase levels, which are key contributors to fibrogenesis and portal hypertension." (PMID 40444235, 2025). "MPO is a well-known enzyme, primarily released by the activated neutrophils, which promotes the production of ROS and reactive nitrogen species in the cells and plays an important role in the pathogenesis of several liver disorders." (PMID 33467773, 2021). "Additionally, in humans with inflammatory liver diseases, increased oxidant production by Kupffer cells from hepatic inflammation can increase levels of MPO locally." (PMID 32442236, 2020). "These two cytokines, MPO and MMP-9, may act in concert with the LCN2 protein and are involved in liver diseases, such as NAFLD/NASH." (PMID 36012166, 2022). "We could further show that in patients undergoing liver resection plasma levels of CitH3, MPO, and NE correlate with hepatic dysfunction markers including aspartate aminotransferase, ALT, and bilirubin, further confirming a possible functional role of neutrophils and NETs in liver diseases." (PMID 38099865, 2024).
malnutrition (15 papers, 2016 to 2025). Inadequate nutrition resulting from poor diet, malabsorption, or abnormal nutrient distribution. "The patient presented in this study has a complex clinical presentation, diagnosed with CNO and total MPO deficiency together with severe systemic inflammation and progressive malnutrition." (PMID 37954595, 2023). "We describe a female patient suffering from severe chronic non-bacterial osteomyelitis (CNO) with systemic inflammation and advanced malnutrition and complete deficiency of myeloperoxidase (MPO)." (PMID 37954595, 2023). "Under malnutrition conditions, they reported decreased mRNA expression of genes associated with regeneration and mesenchymal stem cell accumulation, along with an increase in myeloperoxidase and IL-1β mRNA expression." (PMID 40077629, 2025). "Since CNO is rarely associated with such severe systemic inflammation and advanced malnutrition as seen in this patient, we were prompted to ask if and how the MPO deficiency may contribute to the disease mechanism of this patient." (PMID 37954595, 2023). "Different studies showed that LT-ETEC was associated with increased MPO and malnutrition." (PMID 35873159, 2022). "We found similar results for serum sCD14 levels (pg/mL) (P = 0.001) and fecal MPO levels (ng/mL) (P = 0.01) at 3 months and subsequent malnutrition (wasting)." (PMID 33886672, 2021). "We have previously demonstrated the tight correlation of fecal biomarkers lipocalin-2 (LCN-2) and myeloperoxidase (MPO) with malnutrition and disease burden in the MAL-ED study in children." (PMID 29661930, 2018). "Despite these limitations, we believe that the results suggest that biomarkers of EE like fecal MPO and serum EndoCab and sCD14 levels in children at early ages are predictive of subsequent malnutrition and that MPO, in particular, is a marker of the burden of previous enteric infections." (PMID 33886672, 2021). "Simultaneous, quantitative MPO, FL, FC and Lcn-2, levels were determined in frozen fecal specimens collected from 78 children (mean age 15.2 ± 5.3 months) in a case-control study of childhood malnutrition in Brazil." (PMID 27746954, 2016). "Unpublished data from our group using a neonatal model of cryptosporidiosis and malnutrition in mice showed increased fecal, serum, and prefrontal cortex levels of MPO, suggesting that abnormally high MPO signaling could be a promising target for intervention to break this gut-brain axis disruption." (PMID 37111572, 2023). "Biomarkers such as fecal MPO, serum EndoCab and sCD14 in children at an early age may be useful as a measure of cumulative burden of preceding enteric infections, which are predictive of subsequent malnutrition status and may be useful non-invasive biomarkers for EE." (PMID 33886672, 2021). "The median biomarker values from our sub-study population also differed substantially from those observed in the Malnutrition and Enteric Diseases (MAL-ED) study, which assessed AAT, MPO, and NEO in stool samples from young children in India." (PMID 33684111, 2021). "In the PROVIDE study, selected predictors such as HAZ at week 18, MPO at week 12, and soluble CD14 at week 18 offer a potential explanation for the burden of malnutrition problems in low-income countries, allow early identification of infants at risk, and suggest pathways for intervention." (PMID 28293424, 2017). "The establishment of cut-off values for the common EED biomarkers (MPO, A1AT, and NEO), which play a role in intestinal inflammation, in children with malnutrition has not yet been accomplished." (PMID 38255381, 2024).
pulmonary edema (15 papers, 2009 to 2024). Accumulation of fluid in the lung tissues causing disturbance of the gas exchange that may lead to respiratory failure. "Taraxerone also reduced pulmonary edema, lowered the W/D ratio, suppressed the MPO activity, and decreased the counts of inflammatory cells and the proportion of macrophages with the M1 phenotype." (PMID 39543653, 2024). "Reduced lung inflammation and pulmonary edema.Reduced MPO activity and IL-1β level.Increased IL-10 level." (PMID 32519302, 2020). "Kaempferol treatment attenuated pulmonary edema, pulmonary capillary permeability, myeloperoxidase (MPO) activity, and the numbers of inflammatory cells." (PMID 33057955, 2020). "Further, EPC exosomes reduced myeloperoxidase (MPO) activity, lung injury score, and pulmonary edema, demonstrating protection against lung injury." (PMID 30760290, 2019). "The main findings of this study are that VILI is associated with pulmonary edema, increased levels of BALF inflammatory cytokines IL-1β, IL-6, and RANTES, neutrophil counts, MPO activity, lung Rho activation, and ultrastructural damage of alveolar endothelium." (PMID 25019086, 2014). "We also found that the baicalin pretreatment for 12 h could decrease the MPO content and wet/dry (W/D) weight ratio, which indicates that baicalin can significantly reduce pulmonary edema." (PMID 36838858, 2023). "BBG administration decreased mature interleukin-1β, myeloperoxidase, and matrix metallopeptidase-9 activation, but increased tight junction proteins, such as ZO-1 and occludin, which ameliorated pulmonary edema via anti-inflammation and improved neurological deficits." (PMID 24533168, 2014). "We also report that NT-1 decreased Myeloperoxidase (MPO) activity and ameliorated pulmonary edema." (PMID 38345562, 2024). "Here, we observed that at 24 h post-CS (but not at 4 or 12 h) there was a marked increase in pulmonary edema (PE), neutrophil influx, myeloperoxidase (MPO) levels, and cytokine expression sham (Sh) WT mice." (PMID 33746973, 2021).
steatosis (15 papers, 2012 to 2025). Increased lipid within the cytoplasm of cells. "Neutrophil elastase deficiency decreases the liver steatosis and inflammation in Western diet fed mice, while the myeloperoxidase (MPO) deletion ameliorates hepatic inflammation and fibrosis in HFD mice." (PMID 33384662, 2020). "Consistent with this study, we found that the decreased level of IL-1β was accompanied by the ameliorated steatosis and ballooning liver injury and less MPO positive cells when supplementation of MFGM in rats." (PMID 35308293, 2022). "The MPO data were confirmed histologically, as neutrophil influx was higher in the liver of animals with combined steatosis and cholestasis compared to cholestatic livers." (PMID 27535001, 2016). "Compared with the SBS group, the SBS+MFGM group showed lower liver pathology scores of steatosis and inflammation, less MPO positive cells and reduced expressions of NLRP3, apoptosis-associated speck-like protein containing a CARD (ASC), Caspase-1, interleukin (IL)-1β(P < 0.05) in the liver." (PMID 35308293, 2022). "Previous studies suggested that MPO could be a good noninvasive biomarker to distinguish NASH from steatosis." (PMID 32824349, 2020). "Excessive neutrophil influx and consequent MPO release could be a source of ROS, which may stimulate disease progression and further neutrophil influx in animals with combined steatosis and cholestasis." (PMID 27535001, 2016). "In vitro, oxidative products derived from MPO activate tumor growth factor (TGF)β, and in vivo treatment of mice with a TGFβ inhibitor reduced steatosis and fibrosis." (PMID 35039631, 2022). "Moreover, neutrophil effectors such as elastase (NE), myeloperoxidase (MPO), and human neutrophil peptides (HNP-1) have been shown to exacerbate liver inflammation, IR, steatosis, and fibrosis in MASLD." (PMID 40868256, 2025). "However, hepatic myeloperoxidase (MPO) activity, a measure of the degree of neutrophil influx, tended to be higher (7.4-fold) in animals with combined steatosis and cholestasis in comparison to cholestasis." (PMID 27535001, 2016). "Moreover myeloperoxidase (MPO), an oxidant-generating neutrophil enzyme, has been suggested to be involved in prompting lipid peroxidation in steatotic livers, a process that favours the evolution from simple steatosis to steatohepatitis." (PMID 24084730, 2013).
acute promyelocytic leukemia (14 papers, 2010 to 2023). An aggressive form of acute myeloid leukemia (AML), characterized by arrest of leukocyte differentiation at the promyelocyte stage, due to a specific chromosomal translocation t(15;17) in myeloid cells. "The acute promyelocytic leukemia‐like phenotype CD34(−)/HLA‐DR(−)/MPO(str+) was present in nearly half the patients (48%) and beneficially influenced RFS and OS." (PMID 36808479, 2023). "Pro-myeloperoxidase (pro-MPO), an enzymatically active precursor of myeloperoxidase (MPO), is known to be secreted from cultured bone marrow and promyelocytic leukemia cells, but evidence for the presence of pro-MPO in circulation is lacking." (PMID 29590135, 2018). "LCCs stimulated the iodination of myeloperoxidase-positive human monocytes, neutrophils, and promyelocytic leukemia that may be involved in the bacterial killing mechanism." (PMID 30881983, 2019). "The HL60 promyelocytic leukemia cell line replicates many of the attributes of promyelocytes and careful biochemical experimentation in these cells has produced much of what we currently understand about the biosynthesis of MPO." (PMID 26890638, 2016). "Therefore, studies of MPO biosynthesis have relied heavily on HL60 promyelocytic leukemia cells that, similar to bone marrow-derived promyelocytes, endogenously express, process and store MPO." (PMID 26890638, 2016). "Giant inclusions and Auer bodies in promyeloblasts were investigated in a study which included transmission electron microscopy (TEM) for morphology and ultrastructural cytochemistry for myeloperoxidase in 10 patients with acute promyelocytic leukemia (APL)." (PMID 37228776, 2023). "According to the analysis of myeloid blast population, nearly half of NPM1mut patients show an acute promyelocytic leukemia (APL)-like antigen expression feature represented by CD34(−)/HLA-DR(−)/MPO(str+)." (PMID 34238278, 2021). "The MPO -463G>A (rs2333227) polymorphism may result in a decreased enzyme activity and even greater association with AML, since homozygotes for the G allele correspond to 80% of cases of acute promyelocytic leukemia." (PMID 30154939, 2018). "For example, one could imagine that high levels of MPO precursors may be diagnostic of promyelocytic leukemia but not cardiovascular disease." (PMID 26890638, 2016). "The typical phenotype of acute promyelocytic leukemia (APL) is myeloperoxidase positive and CD33 positive, human leukocyte antigen (HLA)-DR negative." (PMID 21547051, 2010). "Thus, the top two AML genes, MPO (myeloperoxidase) and PML (promyelocytic leukemia) have the GCHs 22.96 and 21.95, below those of the 56th and the 59th ranked ribosomal proteins RPL29 (23.64) and RPL13 (22.12)." (PMID 31349573, 2019). "Interestingly, marrow LRP expression was significantly higher among known favorable prognostic factors, i.e., acute promyelocytic leukemia (APL; M3), and negative MPO." (PMID 30674943, 2019).
cerebral infarction (14 papers, 2014 to 2025). An ischemic condition of the brain, producing a persistent focal neurological deficit in the area of distribution of the cerebral arteries. "Targeting MPO with inhibitors or gene deficiency significantly reduced brain infarction and improved neurological outcomes." (PMID 32508671, 2020). "However, an analysis of >1700 adults enrolled in the Framingham Heart Study found that WMH and silent cerebral infarcts were associated with lower MPO while cerebral microbleed was associated with higher MPO." (PMID 37475160, 2023). "Resveratrol dramatically lowered the amounts of cerebral infarcts, neuronal damage, MPO activity, and evans blue (EB) content in addition to neurological impairment scores." (PMID 39082038, 2024). "An anti-neutrophil monoclonal antibody (RP3) is capable of inhibiting the activity of MPO within 24 h of injection, thereby decreasing brain edema and cerebral infarction in ischemic brain tissue." (PMID 37266435, 2023). "Neutrophil depletion by using an anti-neutrophil monoclonal antibody (RP3) completely inhibited MPO activity, attenuated brain edema and reduced brain infarction in the ischemic brain after 24 h of reperfusion." (PMID 32508671, 2020). "In addition, increased expression of other inflammatory markers, such as intercellular adhesion molecule 1, and decreased levels of myeloperoxidase, were associated with more severe WMH and the occurrence of cerebral infarctions in CSVD patients." (PMID 41000387, 2025). "In addition, MLIF decreased cerebral infarction areas and the level of malondialdehyde (MDA), myeloperoxidase (MPO), tumor necrosis factor-alpha (TNF-α), and IL-1β and increased the level of superoxide dismutase (SOD)." (PMID 34220513, 2021).
chronic heart failure (14 papers, 2014 to 2025). "Myeloperoxidase (MPO) is an enzyme secreted by leukocytes that is a marker of oxidative stress with proatherogenic and pro-oxidant properties, that was found elevated in chronic heart failure." (PMID 40362309, 2025). "In endocardial endothelial cells of patients with chronic heart failure, it was also reported that only through noxious stimuli do they generate MPO." (PMID 39456241, 2024). "In epidemiological studies, a correlation of elevated MPO in chronic heart failure (CHF) was demonstrated even after adjustment for B-type natriuretic peptide (pBNP) or age." (PMID 33344515, 2020). "A prognostic role of MPO has been reported in acute myocardial infarction, acute and chronic heart failure, and also healthy middle age or elderly subjects." (PMID 26539521, 2015). "We evaluated the effects of levosimendan-treatment on MPO in patients with acute decompensation of chronic heart failure over a one week course." (PMID 25867530, 2015). "A significant association between MPO levels and H-FABP levels was also observed in patients with chronic heart failure, indicating that increased MPO levels may contribute to ongoing myocardial damage in these patients." (PMID 34073616, 2021). "Myeloperoxidase (MPO), a leukocyte-secreted enzyme that generates reactive oxygen species during inflammatory processes, is also elevated in chronic heart failure patients, further exacerbating myocardial injury." (PMID 40528106, 2025). "Primary cultures of human endocardial endothelial cells (EEC) from the hearts of patients with chronic heart failure (CHF) and HUVECs that were subjected to H2O2-induced oxidative stress (60 μM) led to MPO expression." (PMID 37507899, 2023).
endometriosis (14 papers, 2011 to 2025). The growth of functional endometrial tissue in anatomic sites outside the uterine body. "In endometriosis, MyeloPerOxidase (MPO) levels are significantly elevated during the proliferative phase." (PMID 39791759, 2025). "Vitamins E and C administration decreased the levels of the oxidative stress marker myeloperoxidase (MPO) in follicular fluid from patients with severe endometriosis." (PMID 38664755, 2024). "Rats with endometriosis displayed an activation of the phagocytic cells in the innate immune system, as evidenced by the increased MPO activity in this inflammatory condition." (PMID 37511500, 2023). "In this inflammatory condition, the innate immune system activates the phagocytic cells as shown by the increased MPO activity in the endometriosis rats." (PMID 34064310, 2021). "In particular, CDDO-Me administration reduced the histopathological signs of endometriosis and inflammatory cells recruitment into the lesions, as shown by toluidine blue staining and myeloperoxidase (MPO) activity." (PMID 33924360, 2021). "Parallel to increased expression of MPO in inflammation, research has demonstrated elevations in macrophage concentration and activity in conditions such as polycystic ovarian syndrome and endometriosis related infertility." (PMID 26982351, 2016). "For example, it has been shown that in advanced stage endometriosis compared with early stage, neutrophil activity with expression of MPO, and thus HOCl are higher secondary to either suppression of phagocytic activity or establishment of neovascularization." (PMID 26197395, 2015). "In addition, açaí reduced the COX-2 expression and PGE2 levels in an experimental model of endometriosis and reduced the MPO levels in a rat renal ischemia/reperfusion model." (PMID 29966007, 2018). "Hidrox® administration was able to restore the oxidative balance in rat hippocampus subjected to endometriosis by managing GSH levels, SOD and MPO activity and lipid peroxidation." (PMID 34064310, 2021). "The administration of vitamins E and C significantly decreased the myeloperoxidase levels in follicular fluid, but not plasma, in moderate/severe endometriosis." (PMID 40130159, 2025). "High levels of MPO have been found in the collected peritoneal fluid samples of patients with chronic genital diseases, polycystic ovarian syndrome (PCOS), advanced stages of endometriosis, and pelvic inflammatory disease." (PMID 26982351, 2016). "In our endometriosis mouse model, knocking down neutrophil recruitment with α-CXCR2 into the peritoneum decreased endometrial tissue adhesion — supported by decreased levels of myeloperoxidase and neutrophil elastase in both developing lesions and peritoneal fluid." (PMID 39836475, 2025).